IL10 (interleukin 10)
Diseases named in the same sentence as IL10 in open-access papers (continued):
Sharing a sentence is not in itself a finding about the gene and the disease.
RSV bronchiolitis (11 papers, 2006 to 2025). "For example, children with IL-10 -592 CC or -592 AA genotypes had a higher risk of hospitalization for RSV bronchiolitis than those with heterozygous genotype." (PMID 33953642, 2021). "Increased IL-10 production has been associated with recurrent wheezing in children hospitalized for RSV bronchiolitis." (PMID 16719922, 2006). "Furthermore, homozygosity for certain IL-10 alleles correlates with a higher risk of severe RSV bronchiolitis." (PMID 21829368, 2011). "Additionally, heterozygosity of the single-nucleotide polymorphism (SNP) rs1800872 in the IL10 promoter region was associated with protection against RSV bronchiolitis." (PMID 21910858, 2011). "The serum level of IL-3, IL-4, IL-10, and IL-13, which originate from Th2 cytokine, were higher in children with RSV bronchiolitis secondary wheezing, and IL-3 can be used as a predictor of recurrent wheezing." (PMID 33691633, 2021). "In our previous study, ex vivo monocyte IL-10 production during the convalescent phase of RSV bronchiolitis was shown to be higher in infants with PBW compared to infants without PBW." (PMID 21910858, 2011). "Interleukin-10, an anti-inflammatory/regulatory cytokine, has been shown not only to be an important component of the pathogenesis of acute RSV bronchiolitis but to also play a role in the enhanced airway hyperreactivity that occurs after RSV infection." (PMID 17961258, 2007). "In our study, motavizumab significantly decreased serum concentrations of KC (chemoattractant for neutrophils, the predominant lung inflammatory cell during acute RSV) and IL-10, two cytokines that play a major role in the pathogenesis of RSV bronchiolitis." (PMID 17961258, 2007). "Treatment with salmeterol alone resulted in a significantly higher percentage of IL-4-producing cells characteristic of the Th2-type response observed in human infants suffering from acute RSV bronchiolitis while FPS decreased both IL-10 and IL-4." (PMID 16719922, 2006). "Most of the data showed the benefit of increased IL-10 in the acute phase of RSV bronchiolitis, but in later phases, including the convalescent phase, the effect might be adverse." (PMID 40430746, 2025). "Bont and colleagues showed that IL-10 levels, measured in the convalescent phase of RSV bronchiolitis in infants 3–4 weeks after the hospitalization, were significantly higher in children who developed recurrent wheezing during the following year than in those without recurrence." (PMID 38397331, 2024). "An alternative hypothesis is based on our previous observations that children with severe RSV bronchiolitis have a stronger local IL-10 response, which may partially be genetically determined." (PMID 24498037, 2014). "This may be particularly evident among children hospitalized for RSV infection where those children with symptoms of severe RSV bronchiolitis requiring mechanical ventilation express lower levels of IL-10 than hospitalized children with less severe disease." (PMID 21829368, 2011). "However, another study has reported no significant changes in IL-10 levels in RSV bronchiolitis and a lack of association with disease severity." (PMID 40430746, 2025). "The relationship between high local IL-10 levels during the initial RSV infection and physician diagnosed PBW provides further evidence of the importance of the IL-10 response during RSV bronchiolitis." (PMID 21910858, 2011). "This study aimed to determine the in vivo role of IL-10 in RSV pathogenesis and recurrent wheeze in a new cohort of 235 infants hospitalized for RSV bronchiolitis." (PMID 21910858, 2011). "Higher IL-10 levels in the airways of infants with RSV infection are observed in infants who subsequently develop physician diagnosed PBW, emphasizing the importance of regulation of the local immune response during RSV bronchiolitis." (PMID 21910858, 2011).
RSV bronchiolitis (continued). "Previously, a correlation was observed between increased ex vivo production of IL-10 from non-specifically stimulated monocytes during the convalescent phase of RSV infection and recurrent wheezing in infants during the year following RSV bronchiolitis." (PMID 40430746, 2025).
syphilis (11 papers, 2017 to 2026). A contagious bacterial infection caused by the spirochete Treponema pallidum. "The authors indicated an association between increased IL-10 levels and the primary stage of syphilis in HIV-infected patients, even though the CD4+ T cell response was low." (PMID 39770782, 2024). "In 35 syphilis patients and 24 healthy volunteers, polymorphisms in the IL10 gene (G>A) polymorphism at position −1084 and C>A polymorphism at position −592 were evaluated." (PMID 37937275, 2023). "We evaluated the serum expressions of IFN, TNF, IL-10, TGF-β1 and IL-17 in men living with HIV (MLWH) and their association with distinct stages of syphilis." (PMID 41901736, 2026). "In lesions typical of primary and secondary syphilis, elevated expression of IL-10 has been observed." (PMID 39770782, 2024). "Above all, IL-10 was expanded significantly, with levels of 12.8 pg/mL to 46.7 pg/mL at the time of syphilis diagnosis, which decreased to 13 pg/mL after antibiotic treatment." (PMID 36291681, 2022). "IL-10 is a potent anti-inflammatory cytokine, and excessive production of IL-10 has been observed in late syphilis." (PMID 33083463, 2020). "In syphilis patients, TpF1 promotes the release of IL-10 and TGF-β from monocytes, potentially driving Treg cell differentiation." (PMID 31024549, 2019). "Of the 11 individuals, his baseline syphilis contained the highest or second highest levels of IL-10, IFNα, CCL4 and IP-10 (Participant 11)." (PMID 30253745, 2018). "The individual with an initial syphilis at study inclusion had a more pronounced elevation in IL-10, IFNα, CCL4 and IP-10 than the individuals with repeat syphilis." (PMID 30253745, 2018). "In the two individuals for which we were able to test their cytokine profile before, during and after PSS infection there was an increase in IL-10 at the time of infection and a return to pre-syphilis values after 6 months." (PMID 28143443, 2017). "At 6 months post syphilis treatment the levels of IL-10 had declined in all groups, and most strikingly in the HIV-infected PSS group." (PMID 28143443, 2017). "They noted a stepwise increase in IL-10 production from primary syphilis to secondary and latent syphilis that correlated inversely with the ability to produce IL-2 (a Th1 cytokine)." (PMID 28143443, 2017). "Syphilis increases the recruitment of HIV-1 susceptible inflammatory cells, such as activated macrophages and CD4+ and CD8+ T cells, to the infection site, leading to an increase in HIV viral load, a decrease in CD4+ T-cell counts, and high TNF-α and IL-10 levels." (PMID 31024549, 2019). "Some scholars found that such cytokines IL-6, IL-10, TNF-α are involved in the pathogenesis and development of syphilis, with the progression of the disease cellular immune function being somewhat suppressed." (PMID 35669916, 2022). "Patients with neurosyphilis had significantly greater levels of IL-10 than those with syphilis but not neurosyphilis." (PMID 37937275, 2023). "A diagnosis of syphilis in humans and animal models is typically characterized by elevations in both plasma pro-inflammatory (TNFα, IFNγ, CCL4, IP-10) and anti-inflammatory cytokines (IL-10)." (PMID 30253745, 2018). "We prospectively recruited all patients with a new diagnosis of syphilis and tested their plasma for IFNα, IFNγ, IL-1β, IL-12p40, IL-12p70, IP-10, MCP-1, MIP-1α, MIP-1β, IL-4, IL-5, IL-6, IL-7, IL-8, IL-10 and IL-17A at baseline pre-treatment and 6 months following therapy." (PMID 28143443, 2017). "In comparison with the trace CSF levels of all 4 cytokines in non-neurotic syphilis, both non-HIV and HIV-positive CM and TBM significantly increased the CSF IL-6 and IL-10 levels, and TBM considerably increased the CSF IFN-γ and slightly increased the IL-17 levels." (PMID 35720334, 2022).
T-cell lymphoma (11 papers, 2001 to 2025). "B and T cell lymphomas have a different serum cytokine signature, with T cell lymphoma associated with increased levels of IL-6, whilst IL-10 is more prominent in B cell lymphoma–affected canine patients." (PMID 30987001, 2019). "Mechanistically, KCa3.1 activators suppress IL-10 transcription in T-cell lymphoma cells and attenuate IL-10-mediated immune evasion by reducing TAM-derived IL-10 production." (PMID 41155636, 2025). "We previously reported that the activation of KCa3.1 with SKA-31 suppressed IL-10 expression and production in human T-cell lymphoma HuT-78 cells." (PMID 35955737, 2022). "We previously reported KCa3.1 activator-induced reductions in the expression and secretion of IL-10 in IL-10-producing T-cell lymphoma, HuT-78 cells." (PMID 35955737, 2022). "It was confirmed that genetic variations of immune-related genes (such as IL-10) were related to the occurrence of T-cell lymphoma in Asian populations." (PMID 33154947, 2020). "The CSF IL-10 level mildly increased, but the IL-10/IL-6 ratio was 0.16 (<0.72), in one case of T-cell lymphoma involving the leptomeninges." (PMID 27924864, 2016). "In this case-control study, we investigated the association between several genetic variants of immunoregulatory genes (IL-10, TNF/LTA, and CTLA-4) and risk for nasal NK/T-cell lymphoma in a Chinese population." (PMID 26108796, 2015). "T-cell lymphomas such as AITL and PTCL release cytokines like IL-10 and CXCL13, fostering a suppressive and angiogenic environment that drives aggressive behavior." (PMID 40801653, 2025). "For example, B-cell lymphoma may exhibit higher levels of IL-10 and TK1 than T-cell lymphoma, while T-cell lymphoma may show higher levels of IL-6." (PMID 39682357, 2024). "No statistical difference was observed between IL-10 and CTLA-4 haplotypes and NK/T-cell lymphomas." (PMID 26108796, 2015).
thrombosis (11 papers, 2008 to 2025). "Noteworthy, the risk of venous thrombosis was found to be associated with the IL-10 promoter polymorphisms; -592 and − 1059, through down-regulation to tissue factor (TF) expression." (PMID 38287362, 2024). "The authors demonstrated that IL-10 G13 and G10 alleles are independent risk factors for venous thrombosis (Odds ratio 3.33 and 2.83 respectively)." (PMID 19578498, 2008). "The second, IL-10, was chosen based on evidence that it may be associated with decreased risk and perhaps may even have a protective effect on deep vein thrombosis." (PMID 34159469, 2021). "Compared with the sham groups, DVT groups showed obvious thrombosis, and IL-10 and TGF-β1 were down-regulated." (PMID 38572308, 2024). "This may justify the findings of this study, which indicated a connection between increased IL-10 and thrombosis." (PMID 37112918, 2023). "Furthermore, recombinant IL-10 inhibits thrombosis in vivo and contrary to this, individuals with depressed levels of IL-10 show enhanced levels of arterial and venous thrombosis." (PMID 34205443, 2021). "In another case-control study, the authors observed that IL-10 G13 allele was an independent risk factor for VTE and IL-10 G10 allele may be an independent risk factor not only for venous thrombosis but also for recurrent disease, considering the fact that it was more frequent in recurrent disease." (PMID 32168924, 2020). "IL-10 was also highest in the thrombosis group relative to non-thrombosis and controls, potentially indicating a compensatory anti-inflammatory effect." (PMID 40776916, 2025). "The baseline levels of IL-6, IL-10, VCAM-1, CCL19, BCA-1, IL-4, E-selectin, fractalkine, CXCL12, and GCP2 were found to differ statistically among the control, arterial thrombosis, AF-related venous thrombosis, and major bleeding groups (p < 0.05)." (PMID 36211709, 2022).
thyroid (11 papers, 2009 to 2026). "IL-10 mitigates inflammation in early thyroiditis by inhibiting Th1 cytokines like TNF-α and IL-1, while in later stages, Th2 cell activation promotes humoral responses." (PMID 39104791, 2024). "Serum level of IL-6, IL-7, IL-10, and IL-13 was higher in thyroid disease, while IL-8 was lower than healthy controls." (PMID 32655554, 2020). "Serum levels of IL-7, IL-10, and IL-13 are higher in thyroid diseases than healthy controls." (PMID 32655554, 2020). "Due to the potentially normalizing effects of anti-thyroid treatment, differences between patients and healthy donors with respect to IL-10 production may have been underestimated in this study." (PMID 26016954, 2015). "They concluded that the reduction number of Breg cells with expression of CD19+CD24hiCD27+IL-10+and CD19+IL-10+(B10) could be responsible for loses immune tolerance and development of autoimmune process in thyroid disorders." (PMID 29449887, 2018). "There is a lack of evidenceregarding IL-10 and nonautoimmune thyroid disorders." (PMID 19343192, 2009). "Importantly, although B7.1wa DCs induce higher IL17 response, profoundly suppressed autoantibody and thyroiditis severity in EAT mice treated with these DCs suggest that this, especially in association with robust Treg and IL10 responses, is not a pathogenic response." (PMID 31427630, 2019). "Different models of thyroid damage applied in the experiment resulted in no significantly different effects on the TNF-α, IL-6, and IL-10 levels." (PMID 30927245, 2020).
trachoma (11 papers, 2008 to 2024). "Upregulation of IL10 expression has previously been reported in individuals with active trachoma and a genetic polymorphism in IL10 was associated with trachomatous scarring." (PMID 28966918, 2017). "The protective effects of the MMP9 Q279R G allele were transformed to risk in the copresence of a SNP (IL10-1082) tagging the trachoma risk haplotype (IL10-3575A~IL10-1082C~IL10-592G~IL10+5009G)." (PMID 26424969, 2015). "Excessive levels of IL10 levels in conjunctiva are a risk factor for scarring and blindness during CT-associated trachoma." (PMID 19397832, 2009). "Conversely, a pathogenic role for the Th3/Tr1 cytokine IL-10 (r = 0.180, P<0.05) was evident with increased levels for all trachoma grades." (PMID 18628987, 2008). "Active trachoma in Gambian children has also been associated with the IL-10 -3917-G allele." (PMID 20552021, 2010). "For example, poor facial cleanliness and presence of flies are risk factors for active trachoma, while genetic polymorphisms in TNF-α, IFNγ, IL-10, IL8, and CSF2 have been linked to risk of trachomatous scarring." (PMID 37287960, 2023). "In our study, IL-10 was overproduced during all grades of trachoma and with C. trachomatis infection." (PMID 18628987, 2008). "While there were too few participants with active trachoma (clinical grades F > 1, P > 2, n = 2) to detect changes in active disease, IL-10, IL-8 and CXCL1 were significantly increased in those with clinical grades F > 0 or P > 0 (p = 0.0031, 0.014, 0.037 respectively, logistic regression)." (PMID 37862368, 2023). "Polymorphisms in key immune genes such as IL-10 and gamma-interferon have been shown to be more frequent in cases with severe trachoma than in normal controls, although these were not replicated in genome-wide association screening." (PMID 27603015, 2016). "Further investigations are needed to clearly define the role of IL-10 for each trachoma grade." (PMID 18628987, 2008). "Furthermore, conjunctival FOXP3 expression is increased in active trachoma, suggesting that regulatory T cells might be present and contribute to tear IL-10." (PMID 37862368, 2023). "However, the role of Tregs and IL-10 in trachoma remains unclear; dampening inflammation might result in less tissue damage, but conversely it might also prolong survival of C. trachomatis." (PMID 28966918, 2017). "No SNP(PEMMAX < 0.01) was detected in any of thegenes IL8, IL10, CSF2, IFNG, HP, CCL8 or MMP9; all of which had beenpreviously reported to associate with trachoma." (PMID 26616738, 2015). "However, elevated IL-10 levels persisted in the presence of C. trachomatis infections regardless of trachoma grade." (PMID 18628987, 2008).
triple-negative breast carcinoma (11 papers, 2018 to 2025). An invasive breast carcinoma which is negative for expression of estrogen receptor (ER), progesterone receptor (PR), and human epidermal growth factor receptor 2 (HER2). "Indeed, high expression of IL-10 was associated with poor survival in pancreatic and triple-negative breast cancer patients." (PMID 30871158, 2019). "The TAMs infiltrating triple-negative breast cancer cells secrete IL-10, which contributes to tumor progression." (PMID 40710006, 2025). "A statistically significant increase in the content of MCP-1, IL-1β, IL-2, IL-4, and IL-10 was found in triple negative breast cancer." (PMID 36286034, 2022). "IL-10 trap alone significantly reduced tumor growth and enhanced median survival over one month, indicating efficacy in immunosuppressive triple negative breast cancer." (PMID 30871158, 2019). "The upregulation of IL10 in tissue and serum was observed in triple-negative breast cancer patients and strongly correlated with increased tumor stage and poor outcome." (PMID 32047513, 2019). "On the other hand, IL-10 expression was reported to be associated with good prognosis in early-stage invasive breast cancer patients (non-triple-negative breast cancer (non-TNBC))." (PMID 33003428, 2020). "Bevacizumab increased the amount of non-classical M2b subpopulation CD11b+ CD86+ IL-10+ of TAMs in a triple-negative breast cancer (TNBC) model." (PMID 34209679, 2021).